MAVS (mitochondrial antiviral signaling protein)
Diseases named in the same sentence as MAVS in open-access papers (continued):
Sharing a sentence is not in itself a finding about the gene and the disease.
infection (continued). "However, we did not observe enrichment of MAVS or IRF3 with SGs assembled in response to Zika virus (ZIKV) or West Nile virus (WNV) infection." (PMID 38295168, 2024). "In addition, Western blot results showed that compared with control cells, in 293T cell line knockout of HDAC8 significantly reduced the protein expression of RIG-I, MAVS, p-TBK1 and p-IRF3 during VSV-GFP infection, which are key regulators of RLRs signaling pathway and subsequent immune response." (PMID 39035358, 2024). "According to previous reports, during infection with several RNA viruses, NOD2 is activated and leads to the activation of a protective innate immune response mediated by interactions with adaptors including RIP2, MAVS, OAS2, CARD9, etc., resulting in activities against the pathogens." (PMID 38668261, 2024). "As MAVS was not completely degraded until 12 h p.i., the remaining MAVS present early in infection (4 and 8 h p.i.)might account for IRF3 phosphorylation in cells infected with NSP1 mutant virus (rSA11-NSP1-35TAA)." (PMID 37905816, 2023). "Because the MAVS and IRF3 KOs had a clear effect on the expression of ISGs after intracellular poly I:C stimulation, we investigated whether a similar effect could be observed after SAV3 infection." (PMID 37588594, 2023). "However, we did not see major differences in RIG-I, MAD5, and MAVS protein expression between acute, chronic or co-infected BMDCs during early course of infection." (PMID 33927339, 2021). "Besides, knockout of USP18 in mouse embryonic fibroblast (MEF) cells did not affect the MAVS protein level with the infection of SeV." (PMID 34016972, 2021). "SVCV infection induced MAVS ubiquitination with wild-type Ub and Ub-K48 but not with Ub-K63." (PMID 33600488, 2021). "We observed that genetic deletion of MAVS prevented class I HLA upregulation in response to IAV infection or ectopic expression of mvRNAs or DI RNAs, suggesting that aberrant viral RNAs generated during infection are bound by RIG-I and transduce signals that increase HLA gene expression." (PMID 32321802, 2020). "However, upon transfection with poly (I:C) or infection with Sendai virus, protein expression levels of MAVS were diminished when H7N9 PB1-F2, but not WSN PB1-F2, was expressed, whereas mRNA levels of MAVS remained unchanged." (PMID 32511263, 2020). "No genes are upregulated to this degree in RIG-I-/- or MAVS-/- during either infection." (PMID 32790753, 2020). "Furthermore, in vitro infection of PBMCs but not CD4+ T cells of healthy donors carrying the MAVS minor genotype resulted in decreased levels of viral replication." (PMID 32708557, 2020). "However, we were not able to examine the role of MAVS in B cell responses such as germinal center (GC) formation since MAVS-/- mice died by 9 days after WNV-TX infection." (PMID 31242236, 2019). "However, given that CD8+ T cells are important for clearing infection from tissues and preventing viral persistence, they might also play an important role in protection of WNV MAD-infected MAVS-/- mice after WNV-TX challenge." (PMID 31242236, 2019). "In addition, WNV RNA was still detected in the spleens of MAVS-/- but not WT mice 63 days after infection." (PMID 31242236, 2019). "The fact that MAVS-/- mice control WNV-MAD infection and IFNAR-/- mice do not, is most likely due to the fact that MAVS-/- mice still make type I IFN after WNV infection, possibly downstream of TLR activation, and thus, presumably utilize the IFNAR pathway for protection." (PMID 31242236, 2019). "In contrast, infection of the human origin HT-29 cells with the human RV Wa strain, but not the simian RRV strain, was capable of degrading human MAVS, highlighting a unique pattern of virus-strain host-species co-segregation with the MAVS degradation phenotype." (PMID 30460894, 2018).
infection (continued). "The absence of TNFα secretion in MAVS KO cells correlated with their decreased level of apoptosis in response to SeV infection, and supplementation of MAVS KO cells with TNFα, but not IFNβ, significantly increased apoptosis upon infection with SeV HD or LD." (PMID 28986577, 2017). "Neither STING nor MAVS depletion reduced antibody-dependent signaling 4 hours post infection with either AdV+IgG or HRV+IgG, in agreement with previous results and confirming that the first wave of sensing is primarily dependent on TRIM21 detection of antibody delivery to the cytosol." (PMID 26506431, 2015). "By contrast, in THP-1 cells, which can recognize bacDNA and bacRNA, type I IFN induction did not appear to be influenced by siRNA-mediated knockdown of MAVS during infection with L. monocytogenes, while the type I IFN response to the RIG-I ligand 3P-dsRNA was efficiently downregulated." (PMID 23653683, 2013). "Our results demonstrate that infection of cells with rA2 ΔNS1 does not appear to affect the interaction of RIG-I with MAVS, in contrast to infection by rA2, suggesting that NS1 interference with the interaction between RIG-I and MAVS may be an important factor in RSV infection." (PMID 22383950, 2012). "Infection with RNA viruses or transient transfection with dsRNA can directly and rapidly induce early ISGs, such as ISG15, through IRF3, after activation of the RIG-I/MAVS pathway and recruitment of TRAF3, an essential adapter which recruits the downstream IRF3 kinases TBK1/IKKε." (PMID 22022264, 2011). "Interestingly, later events were comparable between MAVS deficient and wt mice, and there were no major differences in immune cell (neutrophils, inflammatory monocytes, CD4+ and CD8+ T cells) recruitment to the lungs from day 2–9 post primary infection." (PMID 35108347, 2022). "In this context, it is interesting that MAVS affects the quality of the neutralizing antibody response to the pathogenic WNV-TX strain and its derivative RWN, whereas it does not seem to play the same function in infections with the non-pathogenic WNV-MAD or the attenuated NS4b-P38G strains of WNV." (PMID 33104760, 2020). "In order to investigate the development of long-term humoral responses to WNV in the absence of MAVS and to address if MAVS plays an intrinsic role in B cells after WNV infection, we first tested whether or not MAVS-/- mice could survive infection of a less pathogenic form of WNV, WNV-MAD." (PMID 31242236, 2019). "After infection with WNV, mice were monitored daily for weight loss and clinical manifestations of disease, and mice with Mavs−/− Tregs suffered from a nearly identical weight loss compared to mice with WT Tregs, suggesting that the course of disease was not altered when Tregs lacked MAVS." (PMID 28094802, 2017). "However, both SeV- and RSV-induced apoptosis were significantly reduced in MAVS KO cells despite similar or even higher levels of replication compared to WT controls, indicating that virus replication is not the sole determinant of cell fate during infection." (PMID 28986577, 2017). "Interestingly, the cytokines whose levels were increased in HMA+ strains during mBMDM infection in vitro and in PECS ex vivo, including IL6, CCL5, and IL10, are not those that would be expected to change based on interference with known mitochondrial signaling pathways (i.e., MAVS, NF-kB, IRF3/7)." (PMID 24781109, 2014). "Nevertheless, our findings revealed that infection with ECTV results in decreased levels not only of MAVS–STING but also MAVS–RIG-I and MAVS–MDA-5 colocalization in L929 cells, irrespective of mitochondrial network morphology." (PMID 39338909, 2024). "To substantiate this in an infection setting, we observed that σ3 interacted directly only with MAVS, not other RLR components during an MRV infection." (PMID 38757961, 2024).
infection (continued). "We recently showed that the IFN-I antiviral response is essential for the survival of LGTV infections, since mice lacking other distinct components of the IFN-I pathway like MAVS and IFNAR succumb to infection quite rapidly." (PMID 37737190, 2023). "SAV3 infection in control and IRF7-1 KO cells yielded similar titers and no cytopathic effect, while IRF3 and MAVS KOs presented with severe cytopathic effect and increased titers 6 days after SAV 3 infection." (PMID 37588594, 2023). "At 3 h after infection with 100 HA/mL SeV, fixed mNG-RIG-I showed no increase in colocalization with immunolabeled MAVS." (PMID 36521492, 2023). "The expression of the type I/III interferon (IFN) during infection was impaired in MDA5-/- and MAVS-/-, but not in RIG-I-/-, when compared to wild type (WT) cells." (PMID 34488908, 2021). "Western Blot analysis revealed cleavage of TBK1, but not of MAVS or IRF3, during wt FMDV-A12 infection." (PMID 32667958, 2020). "In agreement with our previous observations, ECTVΔvSlfn or ECTV-vSlfnΔp26 infection triggered high levels of IRF3 phosphorylation and these were abolished in the absence of cGAS and STING, but not MAVS." (PMID 32948585, 2020). "Sindbis virus (SINV) or vaccinia virus (VACVΔE3L) infection of wild-type (WT) or OAS1-KO (knockout), OAS2-KO, or MAVS-KO RoNi/7 cells, but not RNase L-KO or OAS3-KO cells, induces robust RNase L activation." (PMID 31719180, 2019). "Here we report that MAVS-/- mice, unlike after infection with WNV-TX, can resist infection by an infectious clone (i.c.)of WNV-MAD and after WNV-MAD infection develop immunity to otherwise lethal WNV-TX." (PMID 31242236, 2019). "Although depletion of mtDNA did not change the expression levels of DDX41, RIG-I, MAVS, and STING, ρ0 HEK293FT cells significantly reduced the IFN-β gene expression after infection with ΔNS1 influenza virus." (PMID 31604929, 2019). "In the absence of MAVS, none of the viruses induced a type I IFN response despite there being high levels of viral RNA following infection with the 6:2 Tky/05 virus." (PMID 29300777, 2018). "The results showed that SeV infection had no obvious effect on the levels of both MAVS and TRAF6 mRNAs within 12 hr after infection." (PMID 29734366, 2018). "We found that the cleavage of MAVS was induced by IBV at 8 h and 12 h post-infection but was not cleaved after 24 h." (PMID 29132350, 2017). "In salmonids, TRIM25, MAVS, MDA5, and RIG-I were induced following infection with an alphavirus although the signaling pathways were not addressed directly." (PMID 28829373, 2017). "As an effective domain of RIG-I, CARD overexpression alone is sufficient to interact with MAVS, resulting in IFN transcription without infection." (PMID 26205406, 2015). "The absence of MAVS and OAS3 in the HEK293 overexpression pulldown likely reflects limitations of this system, as certain interactions may only occur under infection conditions or in a cell type dependent manner." (PMID 40883306, 2025). "Additionally, the T677A virus induced higher expression of interferon stimulated genes (ISG) (RIG-I and IFIT3) at 48 hours post-infection in wild-type HEK293-luc cells, but not in RIG-I −/− or MAVS −/− cells." (PMID 39605425, 2024). "However, during infection in Vero E6 and HEK293T-hACE2 cells, even though SERINC5 levels were reduced by the action of svRNAs, the levels of MAVS did not decrease in parallel." (PMID 36876111, 2023). "However, DDIT3 does not degrade MAVS in the presence of BoHV-1 (DNA virus) infection, indicating that DDIT3 inhibits IFN-I in different ways during infection by DNA and RNA viruses." (PMID 35259065, 2022). "We also found that deletion of signaling molecules that act upstream of type I IFN production including multiple TLRs, RIPK2, cGAS/STING, or MAVS pathways, did not increase BMDM fusion during infection while control BMDMs lacking MyD88 and TRIF or IFNAR1 extensively fused." (PMID 32150572, 2020).
infection (continued). "Notably, infection with EMCV Lpro L143A, which displayed wt deISGylase/DUB activity but is strongly impaired in its ability to cleave/degrade RLR signaling proteins MAVS, TBK1 and NFκB p65, failed to suppress the induction of IFN-β mRNA." (PMID 32667958, 2020). "While we did observe higher WNVE-specific IgG titers in MAVS-/- compared to WT mice following WNV-MAD infection, consistent with observations previously reported with WNV-TX, we also observed elevated nAbs, GC B cells and TFH cells in the absence of MAVS." (PMID 31242236, 2019). "Thus, in RoNi/7 bat cells, as in human cells, activation of RNase L during infection and its antiviral activity are dependent primarily on OAS3 while MAVS signaling is not required for the activation of RNase L and restriction of infection." (PMID 31719180, 2019). "Furthermore, our observation of elevated splenic CD8+ TEFF cells in the absence of MAVS during WNV-MAD infection are consistent with the expansion of CD8+ T cells in the periphery and CNS previously observed in MAVS-/- mice infected with a lethal WNV strain." (PMID 31242236, 2019). "Thus, activation of RNase L during VACVΔE3L infection of bat RoNi/7 cells was dependent on RNase L and OAS3 but not OAS1, OAS2, or MAVS, similar to our findings with SINV." (PMID 31719180, 2019). "As the absence of degradation of MAVS and TRIF in SF268 cells at early stages of infection, we postulated that the difference could be due to the low viral protein levels in these cells." (PMID 31817126, 2019). "MAVS and TRAF3 did not presented a significant down-regulation at 12 h post infection; however, both presented significantly down-regulation at 24 h post infection (2 and 7.4 fold, respectively)." (PMID 29813068, 2018). "Moreover, direct activation of PKR with this approach displayed MAVS-, but not MDA5-dependency, suggesting that the requirement for PKR during VVΔE3L infection lies downstream of MDA5, but upstream of MAVS." (PMID 26939124, 2016). "While in MEFs lacking MAVS no IFN could be detected, in cells ectopically expressing organelle-specific MAVS similar levels of IFN-β were determined at 16 h post infection." (PMID 26588843, 2015). "HCV enters the KC via phagocytic uptake, with no development of the productive infection, and this leads to IFNβ-mediated activation of innate immunity through the RIG1/MAVS pathway and inflammatory signaling through the TLR7/myD88 and NLRP3 inflammasome pathway." (PMID 25664450, 2015). "Infected MAVS−/− and IRF3−/−IRF7−/− epithelia show ISG induction in the absence of any detectable IFN upregulation, while IFNAR1−/−IL-28Rα−/− cells, which produce but cannot respond to IFNs, did not express ISGs in response to infection." (PMID 24278020, 2013). "Inhibition of virus yields did not increase later in infection (36% at 48 hrs post-infection), in agreement with the block on IFN induction downstream of TRIM25 imposed by the NS3/4A-mediated cleavage of MAVS." (PMID 20485506, 2010). "Moreover, MEFs isolated from wild-type, TLR-9−/−, TLR-3−/−, MAVS−/− and MyD88−/− and TRIF−/− C57BL/6 mice embryos were all producing similar levels of IFN-β upon MVMp infection, indicating that neither TLRs nor RLRs are involved in the IFN response triggered by replicating MVMp in MEFs." (PMID 37111493, 2023). "However, as hepatocytes typically express RIG-I and MAVS, we cannot rule out the possibility that PCBP1 may also modulate this pathway during infection in vivo." (PMID 35215884, 2022). "The results showed that siRNAs targeting RIG-I, MDA5, and TRIF but not MAVS or MyD88 significantly reduced the mRNA of IFN-β, demonstrating that RIG-I/MDA5-mediated RLRs signaling pathway and TRIF-mediated TLRs signaling pathway involved in the production of IFN-β during FJzz1 infection." (PMID 35958569, 2022).
infection (continued). "Due to the lack of data of pre-infection MAVS levels in LTNP RMs, it is hard to determine whether higher MAVS expression in Control RMs compared to LTNP and Progressor was caused by SIV infection or it’s only the congenital characteristics of LTNP RMs, it merits further research in the future." (PMID 30326919, 2018).
tumor (62 papers, 2015 to 2026). "Previous studies have demonstrated that DNA‐demethylating agents activate the innate immune system via the MDA5 (melanoma differentiation‐associated protein 5) /MAVS (mitochondrial antiviral‐signaling) RNA recognition pathway in tumor cells." (PMID 34586646, 2021). "The RIG-I/MAVS signaling stimulates anti-tumor immunity by triggering the production of inflammatory cytokines." (PMID 40016186, 2025). "The anti-tumour mechanism of RIG-I agonists is mainly activated by the MAVS/Type I IFN signalling pathway in tumour cells or innate immune cells." (PMID 39322862, 2024). "The B16 model maintains intact cGAS/STING and MDA5/MAVS signaling pathways, like other commonly used transplantable syngeneic tumor models." (PMID 36918588, 2023). "Previous studies have reported that MAVS can be activated by exogenous virus RNA and exert its anti-tumor effect by up-regulating the downstream pro-apoptotic genes TRAIL and Noxa to induce apoptosis in PCa cells." (PMID 37494663, 2023). "The results of the co-expression analysis indicated that MAVS participates in tumor progression by regulating genes involved in oxidative stress and metabolic pathways." (PMID 34722508, 2021). "Altogether these studies on the STING and the MAVS pathway show that triggering of the IFN I response in tumor cells is central to inflame the microenvironment." (PMID 34249754, 2021). "Expression of endogenous retrovirus (ERV) under the form of dsRNA due to epigenetic deregulation in tumor cells can also trigger the expression of IFN I via the MAVS pathway." (PMID 34249754, 2021). "In conclusion, our data provide the first comprehensive demonstration of the role of RIG-I/MAVS pathway in Type I IFN induction in tumor cells exposed to IR and chemotherapy." (PMID 27034163, 2016). "Upstream regulators of the tumor-associated mouse genes significantly altered by metronomic CPA treatment include DDX58, as well as FADD and MAVS." (PMID 25952672, 2015). "Because platinum-/paclitaxel-based chemotherapy following tumor debulking surgery is still the gold standard treatment for OC, we analyzed whether these drugs are related to MAVS expression." (PMID 34722508, 2021). "However, IFN I response in tumor cells can also be induced by the sensing of endogenous dsRNA via the MAVS pathway and that also plays a role in the stimulation of the antitumor immune response." (PMID 34249754, 2021). "DDX58 is a pattern recognition receptor that signals through FADD and MAVS and may contribute to the observed anti-tumor immune responses." (PMID 25952672, 2015). "However, the molecular mechanism underlying the regulation of MAVS activity and its function in anti-tumor immunity is not fully understood." (PMID 40016186, 2025). "Additionally, circNDUFB2 is recognized by RIG-I (Retinoic acid-Inducible Gene I) and leads to activation of the RIG-I-MAVS (Mitochondrial Antiviral Signaling protein) signaling cascade, with consequent immune cell recruitment into the tumor microenvironment (TME)." (PMID 38501058, 2024). "Furthermore, recent research suggests that modulating MAVS signaling could enhance anti-tumor immunity and improve the efficacy of cancer immunotherapy." (PMID 39132148, 2024). "Next, we confirmed that loss of STING or MAVS did not alter tumor growth in B16 CASP3-/-7-/- cells." (PMID 36918588, 2023). "The proposed working model is that ORMDL3 forms a complex with MAVS and promotes the degradation of RIG-I, thereby attenuating the transcription of type I IFN and cytotoxic CD8+ T cell-mediated tumor killing." (PMID 40126553, 2025). "N-MYC inhibited the induction of IFN type I by suppressing tumor cell–intrinsic STING signaling via reduced STING oligomerization, and by blunting RIG-I–like receptor signaling through inhibition of MAVS aggregation and localization in the mitochondria." (PMID 38748789, 2024).